NKX6-2 (NK6 homeobox 2)
Description:
Transcription factor with repressor activity involved in the regulation of axon-glial interactions at myelin paranodes in oligodendrocytes. Binds to the consensus DNA sequence 5'-(A/T)TTAATGA-3'. In oligodendrocytes, binds to MBP and PLP1 promoter regions.
Synonyms: GTX; NKX6B; NKX6.1; NKX6.2; SPAX8
Tractability: No criterion of Open Targets' tractability assessment is met for any kind of drug.
Gene: Protein-coding gene on chromosome 10 (132,783,179 to 132,786,147, reverse strand). Ensembl gene ENSG00000148826.
Subcellular location: Nucleus
Gene Ontology:
Molecular function: sequence-specific double-stranded DNA binding; DNA binding; DNA-binding transcription factor activity; DNA-binding transcription factor activity, RNA polymerase II-specific; RNA polymerase II cis-regulatory region sequence-specific DNA binding; DNA-binding transcription repressor activity, RNA polymerase II-specific; sequence-specific DNA binding
Biological process: cell differentiation; negative regulation of DNA-templated transcription; regulation of DNA-templated transcription; regulation of myelination; regulation of transcription by RNA polymerase II; negative regulation of transcription by RNA polymerase II
Cellular component: chromatin; nucleus
Genetic constraint (gnomAD): Loss-of-function variants: 16 observed, 14.24 expected, observed/expected ratio (o/e) 1.12, 90% interval 0.76 to 1.68. The synonymous counts are far from expectation, so gnomAD's model fits this gene poorly and the ratio says little. Missense variants: 292 observed, 218.26 expected, observed/expected ratio (o/e) 1.34, 90% interval 1.22 to 1.47. Synonymous variants: 162 observed, 111.13 expected, observed/expected ratio (o/e) 1.46, 90% interval 1.28 to 1.66.
Homologues: Orthologues: chimpanzee NKX6-2 (99% identical), macaque NKX6-2 (99% identical), mouse Nkx6-2 (97% identical), pig NKX6-2 (97% identical), rat Nkx6-2 (97% identical), dog NKX6-2 (96% identical), guinea pig NKX6-2 (92% identical), tropical clawed frog nkx6-2 (78% identical), zebrafish nkx6.2 (78% identical), Drosophila melanogaster HGTX (43% identical), Drosophila melanogaster NK7.1 (35% identical), Caenorhabditis elegans cog-1 (27% identical), and 4 more. Paralogues in human: NKX6-1 (67% identical), NKX6-3 (48% identical), NKX1-1 (22% identical), NKX1-2 (21% identical), NKX2-4 (19% identical), NKX2-1 (18% identical), NKX2-2 (18% identical), NKX3-2 (18% identical), NKX3-1 (17% identical), NKX2-3 (17% identical), NKX2-5 (16% identical), NKX2-6 (16% identical), and 1 more.
Diseases named in the same sentence as NKX6-2 in open-access papers:
NKX6-2 is named in the same sentence as 37 diseases in open-access papers, as found by Europe PMC text mining. Sharing a sentence is not in itself a finding about the gene and the disease. The quoted sentences say what the papers report.
bladder cancer (5 papers, 2013 to 2025). "DNA methylation of NKX6-2 has been reported to be associated with aggressive RCC as part of a methylation signature for the detection of bladder cancer and to be a target of hypermethylation in other tumor entities." (PMID 36232491, 2022). "In addition, NKX6-2 methylation also potentially predicts the risk of recurrence and the progression of bladder cancer." (PMID 37627900, 2023). "DNA hypermethylation of NKX6-2 has been detected in lung adenocarcinoma, colorectal carcinoma, and bladder carcinoma." (PMID 36232491, 2022). "The impact of the hypermethylated NKX6-2 gene has been reported in bladder cancer, renal cancer, and lung adenocarcinoma, and this is consistent with our results in colorectal cancer specimens." (PMID 27688749, 2016). "Notably, it has been described as part of a biomarker panel for early bladder cancer detection in urine, and methylome analysis in RCC has suggested that hypermethylation of NKX6-2 is associated with more aggressive RCC, demonstrating shortened overall survival." (PMID 36232491, 2022). "Eight genes (NKX6-2, A2BP1, CA10, DBC1, MYO3A, NPTX2, PENK, and SOX11) were significantly highly methylated in the urine sediments of bladder cancer patients as compared to that of control subjects." (PMID 37627900, 2023). "Similarly NKX6-2 is a methylated biomarker for bladder cancer but its importance and methylation has not been studied in LUAD." (PMID 24369052, 2013).
spastic ataxia (3 papers, 2017 to 2022). "Nkx6-2 is involved in oligodendrocyte maturation and its mutations leads to the hypomyelination and spastic ataxia phenotype in humans." (PMID 36543780, 2022). "Bi‐allelic mutations in NKX6‐2 were recently linked to spastic ataxia 8 with hypomyelinating leukodystrophy." (PMID 31509304, 2020). "Our results support a non-redundant developmental role of NKX6-2 in humans and imply that NKX6-2 mutations should be considered in the differential diagnosis of spastic ataxia and hypomyelination." (PMID 28575651, 2017). "This syndrome confirms the non-redundant role of NKX6-2 in myelin homeostasis in the central nervous system and expands the genetic causes of spastic ataxia, the heterogeneity of developmental genes, and inborn errors of myelin metabolism in humans." (PMID 28575651, 2017).
Ataxia (2 papers, 2020 to 2025). Ataxia refers to impaired coordination of voluntary muscle movement. "NKX6‐2 mutations should be considered in patients with autosomal recessive, very early onset of nystagmus, cerebellar ataxia with hypotonia that rapidly progresses to spasticity, particularly when associated with neuroimaging signs of hypomyelination." (PMID 31509304, 2020). "Likewise, PLP1, NKX6-2, and ATP1A3 mutations are linked to spasticity, ataxia, and cognitive deficits." (PMID 41300846, 2025).
bladder tumors (2 papers, 2016 to 2023). "Previous studies showed that NKX6-2 is hypermethylated in bladder tumors and hypomethylated in normal leukocytes." (PMID 27688749, 2016). "In recurrent and progressed bladder tumors, the frequency of NKX6-2 methylation was higher than that of non-recurrence bladder tumors." (PMID 37627900, 2023).
cognitive deficits (2 papers, 2020 to 2025). "Severe cognitive impairment occurred in patients with mutations in NKX6-2, PLP1, PAH gene (when untreated), and SCN2A (in early-onset type), whereas milder ID was associated with SCN2A (in late-onset type) or SMAD6 variants." (PMID 41300846, 2025). "However, severe cognitive impairment with arrested speech development was present in 66% of all children with bi‐allelic NKX6‐2 pathogenic variants and in all reported children with neonatal onset." (PMID 31509304, 2020).
adenoma (1 paper, 2016). A neoplasm arising from the epithelium. "We identified hypermethylated CpG sites in the following genes: L3MBTL1, NKX6-2, PREX1, TRAF7, PRDM14, and NEFM with the number of CpG sites being 14, 17, 10, 16, 6, and 6, respectively, after pairwise analysis of normal versus adenoma, adenoma versus cancer, and normal versus cancer." (PMID 27688749, 2016).
brain tumors (1 paper, 2010). "NKX6-2 is a transcription factor with known positive and negative regulatory activities in development and differentiation and has been postulated to be a tumor suppressor for some types of brain tumors (e.g., oligodendrogliomas)." (PMID 20485525, 2010).
hypomyelinating leukodystrophy (1 paper, 2020). "Eleven new cases from eight families of different ethnic backgrounds carrying compound heterozygous and homozygous pathogenic variants in NKX6‐2 were identified, evidencing a high NKX6‐2 mutation burden in the hypomyelinating leukodystrophy disease spectrum." (PMID 31509304, 2020). "A new phenotype associated with bi‐allelic mutations in NKX6‐2 leading to spastic ataxia 8 (SPAX8), autosomal recessive, with hypomyelinating leukodystrophy (OMIM: 617560) has recently been described by our group 2." (PMID 31509304, 2020).
metastatic disease (1 paper, 2022). "Therefore, the association of methylation and metastatic disease progression suggests NKX6-2 as a promising candidate for subsequent targeted functional analysis of RCC metastases." (PMID 36232491, 2022).
Seizure (1 paper, 2020). A seizure is an intermittent abnormality of nervous system physiology characterized by a transient occurrence of signs and/or symptoms due to abnormal excessive or synchronous neuronal activity in the brain. "Seizures were present in four (12.5%) patients harbouring NKX6‐2 mutations." (PMID 31509304, 2020).
tubular adenoma (1 paper, 2016). A usually polypoid neoplasm arising from the glandular epithelium. "As for NKX6-2 (NM_177400), we identified 37 methylated CpG sites in promoter region in tumor samples, while none of these CpG sites were found to be methylated in normal, tubular adenoma, and tubulovillous adenoma samples." (PMID 27688749, 2016).
tumor (10 papers, 2010 to 2025). "Of these, 83 were heterozygous novel SNPS, 3 were homozygous in the tumor only, presumably due to LOH, and 3 in NKX6-2, CDH8, and NFRKB were heterozygous point mutations." (PMID 20485525, 2010). "Univariate logistic regression of TCGA KIRC methylation data from 282 tumor tissues, including 232 M0 and 52 M+ tumors, identified three loci annotated for NKX6-2 (cg06082548, cg01384488, and cg19701540) that were associated with the state of distant metastasis in patients." (PMID 36232491, 2022). "NKX6-2 and BTG2 (B-Cell Translocation Gene 2) are candidate tumor suppressor genes." (PMID 27935972, 2016). "The mean methylation level increase from no-recurrence to recurrence and progression tumours was not significant for NKX6-2, SPAG6, ZIC1 and ZNF154." (PMID 26332997, 2015).
cancer (6 papers, 2013 to 2022). A tumor composed of atypical neoplastic, often pleomorphic cells that invade other tissues. "Here we identified specific CpG sites in L3MBTL1, NKX6-2, PREX1, TRAF7, PRDM14,and NEFM as primarily methylated in cancer specimens but not in other colonic lesions; these genes were also found to be implicated in many important pathways relevant to neoplastic transformation." (PMID 27688749, 2016).
NKX6-2 also shares sentences with these, for which no sentence is quoted: glioblastoma (2 papers); adenosquamous carcinoma (1); Anxiety (1); cerebellar ataxia (1); colorectal cancer (1); congenital heart disease (1); diabetes (1); epilepsy (1); Hyperglycemia (1); infection (1); Limb dystonia (1); lung adenocarcinoma (1); neurodevelopmental disorder (1); Nystagmus (1); oligodendroglioma (1); pancreatic cancer (1); prostate carcinoma (1); psychiatric diseases (1); renal carcinoma (1); schizophrenia (1); spastic ataxia 8 (1); Spasticity (1); T-cell leukemia (1); tubulovillous adenoma (1).